CRP (C-reactive protein)
Diseases named in the same sentence as CRP in open-access papers (continued):
Sharing a sentence is not in itself a finding about the gene and the disease.
ductal adenocarcinoma (2 papers, 2005 to 2023). "C-reactive protein to albumin ratio is a significant predictor for survival in ductal adenocarcinoma, yet its clinical relevance should be explored in conjunction with the pathology parameters and adjuvant therapy." (PMID 37322265, 2023). "Patients (n=65) who underwent resection of ductal adenocarcinoma of the head of pancreas between 1993 and 2001, and had pre- and postoperative measurements of C-reactive protein, were included in the study." (PMID 15597096, 2005). "C-reactive protein to albumin ratio, but not Glasgow prognostic score and modified Glasgow prognostic score, was linked to survival following pancreatectomy for ductal adenocarcinoma." (PMID 37322265, 2023). "However, if an elevated C-reactive protein concentration is shown to predict a poorer prognosis, it may be the case that patients with potentially resectable ductal adenocarcinoma of the head of the pancreas, yet a high inflammatory profile preoperatively, should not undergo surgery." (PMID 15597096, 2005).
Ebola virus disease (2 papers, 2021 to 2025). "It was reported that high aspartate aminotransferase, alanine aminotransferase, CRP, and IL-6 levels were closely associated with poorer outcome of Ebola virus disease." (PMID 34447386, 2021). "Although the pathophysiological mechanisms of LF and Ebola virus disease differ, these findings underscore the potential of CRP as a valuable indicator of disease severity in viral hemorrhagic fevers." (PMID 39877415, 2025). "In addition, CRP might be involved in the pathogenesis of Ebola virus (EBOV) disease, which is a severe infectious disease that can cause human and other primates to produce Ebola hemorrhagic fever." (PMID 34447386, 2021).
epiglottitis (2 papers, 2025). Inflammation of the epiglottis. "The remarkable swelling of his larynx, the throat pain, and the elevated CRP suggested an infectious disease and supported the diagnosis of acute epiglottitis." (PMID 39801600, 2025). "A limitation of this case is the lack of collection of inflammatory biomarkers (e.g., CRP, ESR), which may have helped support the immune-mediated nature of these events or aided in monitoring for resolution or recurrence of supraglottitis." (PMID 40936685, 2025).
erythroderma (2 papers, 2014 to 2024). "Among the laboratory parameters, a significant association was observed on admission between the cause of erythroderma and the level of ESR (p = 0.0039), CRP (p = 0.0000), and immunoglobulins IgE (p = 0.0008)." (PMID 38337339, 2024). "C-reactive protein (CRP), on the other hand, was significantly higher in the subjects with drug-induced erythroderma than in those with primary cutaneous lymphomas." (PMID 38337339, 2024). "The median CRP level was highest in patients with drug-induced erythroderma." (PMID 38337339, 2024).
esophageal neoplasm (2 papers, 2015 to 2025). "In addition, there were more patients without resection of esophageal tumors and received palliative treatment in the higher CRP/Alb ratio level group (both P < 0.001)." (PMID 25934640, 2015).
exocrine pancreas insufficiency (2 papers, 2024 to 2025). "However, in the fully adjusted models including exocrine pancreas insufficiency, CRP and fat mass index as covariates the estimates for IGT vs NGT (eβ 1.09, 95% CI: 0.85; 1.41) and CFRD vs NGT (eβ 1.14, 95% CI: 0.91; 1.44) were lower." (PMID 39530118, 2024).
Fabry disease (2 papers, 2013 to 2025). Fabry disease (FD) is a progressive, inherited, multisystemic lysosomal storage disease characterized by specific neurological, cutaneous, renal, cardiovascular, cochleo-vestibular and cerebrovascular manifestations. "There was a trend for low serum levels of IL-6 and high serum levels of TNF-α and high-sensitive CRP in Fabry patients; plasma concentrations of soluble VCAM-1 were significantly higher in Fabry disease patients than in healthy volunteers (p = 0.02)." (PMID 24207059, 2013).
Facial palsy (2 papers, 2021 to 2025). Facial nerve palsy is a dysfunction of cranial nerve VII (the facial nerve) that results in inability to control facial muscles on the affected side with weakness of the muscles of facial expression and eye closure. "All patients with GBS (100%) showed an elevation in CRP and d-dimer levels; however, the findings were not significant in patients with facial palsy and polyneuritis cranialis." (PMID 34679418, 2021).
fibrosarcoma (2 papers, 2021). A malignant mesenchymal fibroblastic neoplasm affecting the soft tissue and bone. "CRP, or its active peptide-fragment, when encapsulated in liposomes, were maximally effective in protecting not only metastases in a murine fibrosarcoma model, but increased survival when liposome-encapsulated CRP (or its peptide) were injected in combination with interleukin-2 (IL-2)." (PMID 34552600, 2021). "Similar to our results, photodynamic therapy of fibrosarcoma induced production (mRNA) of other acute phase proteins (serum amyloid-P (SAP) mannose binding lectin (MBL) and c-reactive protein (CRP))." (PMID 33917524, 2021).
filariasis (2 papers, 2020 to 2021). "The serum protein profiles and CRP concentrations in canine filariasis can reflect the health status of infected dogs." (PMID 34083932, 2021). "Dogs not presenting filariasis evidenced significantly increased CRP rates when suffering from DCM or PH." (PMID 32676505, 2020).
Gastric Varices (2 papers, 2024 to 2025). "Patients with PAD had a higher serum level of CRP when compared to patients with varicose veins (18.07 ± 32.34 mg/L vs. 3.75 ± 3.00 mg/L p = 0.006)." (PMID 38667739, 2024).
gastroschisis (2 papers, 2020 to 2024). Gastroschisis is marked by viscera protruding, without a covering sac, from the fetal abdomen on the right lateral base of the umbilicus. "Infants with gastroschisis tend to have elevated C-reactive protein (CRP) values as well as immature to mature neutrophil count (I:T) ratio, but these are not reliable markers of infection or adverse outcomes." (PMID 33348575, 2020).
generalized pustular psoriasis (2 papers, 2019 to 2026). A rare and extreme form of psoriasis characterized by the appearance of sterile pustules which can take many patterns. "The aim of this study was to evaluate the diagnostic properties and define appropriate cut-off values of procalcitonin and C-reactive protein in predicting bacterial infection in generalized pustular psoriasis patients." (PMID 31777354, 2019). "The serum levels of procalcitonin and C-reactive protein performed equally well to differentiate bacterial infection from non-infection in generalized pustular psoriasis patients." (PMID 31777354, 2019). "The reference value of procalcitonin and C-reactive protein applied to predicting bacterial infection in most clinical cases may not be suitable for generalized pustular psoriasis patients." (PMID 31777354, 2019).
Goodpasture syndrome (2 papers, 2012 to 2023). "The decrease of CRP or procalcitonin in Goodpasture syndrome for instance is thought to be associated with a more favorable outcome." (PMID 22685586, 2012). "Subjects with Goodpasture’s syndrome can have notably elevated CRP concentrations (mean 145.7 mg/L), whereas increased CRP levels (mean 60 mg/L) were evident in 3⁄4 of cases with acute renal infarction." (PMID 37873776, 2023).
graft versus host disease (2 papers, 2018 to 2025). An immune system disorder that occurs after allogeneic hematopoietic stem cell transplant and is a reaction of donor immune cells against host tissues. "G-CSF increased CRP levels especially in elderly donors with high pretherapy levels, but these preharvesting levels did not influence clinical outcomes (nonrelapse mortality, graft versus host disease)." (PMID 30249022, 2018).
Hallucinations (2 papers, 2014 to 2021). Perceptions in a conscious and awake state that, in the absence of external stimuli, have qualities of real perception. "Evidence for association between CRP and auditory hallucinations also remained in sensitivity analyses focusing on more clinically relevant symptoms or excluding participants with preexisting symptoms." (PMID 33229033, 2021). "At individual symptom level, after adjusting for potential confounders including depressive symptoms, CRP was associated with auditory hallucinations (adjusted OR = 2.22; 95% CI, 1.04–4.76) and anhedonia (adjusted OR = 1.13; 95% CI, 1.02–1.26)." (PMID 33229033, 2021). "Evidence for association between CRP levels and auditory hallucinations remained after excluding participants who experienced positive symptoms in the context of cannabis/other drug use, illness or sleep; adjusted OR = 2.49 (95% CI, 1.01–6.17)." (PMID 33229033, 2021). "•CRP was specifically associated with auditory hallucinations and anhedonia." (PMID 33229033, 2021). "High, compared with low, serum CRP levels were associated with auditory hallucinations after controlling for age, sex, BMI, father's occupation, ethnicity, depressive symptoms, smoking, alcohol, cannabis and other drug use; adjusted OR = 2.22 (95% CI, 1.04–4.76)." (PMID 33229033, 2021). "High prevalence is unlikely to explain the association of auditory hallucinations with CRP." (PMID 33229033, 2021).
Helicobacter pylori (2 papers, 2019 to 2025). "Future studies are warranted to evaluate the long-term efficacy and therapeutic potential of CRP in more relevant chronic ulcer models, such as those induced by *Helicobacter pylori* infection." (PMID 40647169, 2025).
hemolysis (2 papers, 2015 to 2026). Disruption of the integrity of the erythrocyte membrane causing release of hemoglobin. "In neonates, longitudinal CA1 trajectories stratified infants into physiological, transient, and sustained hemolysis groups; higher CA1 levels were associated with prematurity, elevated CRP and lower white blood cell count." (PMID 41737922, 2026).
hepatoblastoma (2 papers, 2017 to 2023). Hepatoblastoma (HB) is a malignant hepatic tumor and is the most common pediatric liver cancer. "Three genes identified in our hepatoblastoma analyses were also listed in the top 20 differentially methylated genes during liver development: CRP, NNMT (both hypermethylated) and C3P1 (hypomethylated)." (PMID 29228658, 2017).
hepatocellular adenoma (2 papers, 2017 to 2025). A benign epithelial neoplasm arising from the hepatocytes. "Subclassification of hepatocellular adenoma (HCA) relies on several stains, including liver-fatty-acid-binding protein (LFABP), serum amyloid A (SAA), C-reactive protein (CRP), glutamine synthetase, and β-catenin." (PMID 40869049, 2025).
hereditary angioedema (2 papers, 2019 to 2026). Hereditary angioedema (HAE) is a genetic disease characterized by the occurrence of transitory and recurrent subcutaneous and/or submucosal edemas resulting in swelling and/or abdominal pain. "Laboratory workup with normal complement C4 helped exclude hereditary angioedema, and C-reactive protein (CRP) was mildly elevated, consistent with a nonspecific inflammatory process." (PMID 42226854, 2026).
hippocampal atrophy (2 papers, 2020). "We note that among the top 5 features are the 2 ADNI cognitive performance variables, the plasma analytes Apolipoprotein E and C Reactive protein, as well as right hippocampal atrophy rate." (PMID 32716914, 2020).
hyperaldosteronism (2 papers, 2016 to 2025). Overproduction of aldosterone by the adrenal glands, which may lead to hypokalemia and/or hypernatremia. "These evidences explain the current association of hyperaldosteronism and CRP, adipocytokine release of TNF-α, IL-6 & IL-23 as well as adhesion endothelial markers; ICAM and VCAM and p-selectin." (PMID 27478508, 2016).
Hypercalciuria (2 papers, 2020 to 2025). "Laboratory findings revealed elevated C-reactive protein, hypercalciuria, and increased serum angiotensin-converting enzyme (ACE) levels." (PMID 41567898, 2025).
hypercortisolism (2 papers, 2013 to 2023). "Other authors previously reported divergences in the dynamics of two different APPs, as it appears in cases of hypercortisolism with an increase in Hp but a decrease in CRP or in cases of intravascular haemolysis with a decrease in Hp but an increase in CRP." (PMID 37344860, 2023).
hyperostosis (2 papers, 2021 to 2022). Excessive thickening of bone. "Caffey disease was initially considered as the diagnosis because the patient displayed fever and hyperostosis of multiple bones with elevated erythrocyte sedimentation rates and C-reactive protein and alkaline phosphatase levels." (PMID 34832024, 2021).
hyperprolactinaemia (2 papers, 2022 to 2025). "Several previous studies showed that PRL was associated with increased CRP in individuals with hyperprolactinemia and older adults, whereas it was weakly correlated with CRP in male patients." (PMID 35222274, 2022).
hypersensitivity (2 papers, 2022). An inflammatory response to an exogenous environmental antigen or an endogenous antigen initiated by the adaptive immune system. "Hypersensitivity C-reactive protein (p < 0.0209), Immunoglobulin IgE (p < 0.0003), Hemoglobin (p < 0.0001), White blood cell count (p < 0.0001), Neutrophil percentage (p < 0.0001) and Lymphocytes percentage (p < 0.0001) levels were significantly increased." (PMID 36313877, 2022). "Abnormal renal function test results included Blood urine nitrogen (BUN) 8.71 mmol/L, Creatinine (Cr) 89.0 umol/L; Hypersensitivity C reactive protein (Hs-CRP) 175.35 mg/L." (PMID 35232448, 2022).
Hypervolemia (2 papers, 2014 to 2020). An increase in the amount of intravascular fluid, particularly in the volume of the circulating blood. "Hypervolemia is associated with weight gain and higher C-reactive protein (CRP) levels." (PMID 32138278, 2020).
hypocortisolemia (2 papers, 2012 to 2022). "In sum, the results revealed that at baseline patients presented hypocortisolemia, blunted salivary cortisol awakening response (CAR) and a low-grade pro-inflammatory profile [shown by increased C-Reactive Protein (CRP) levels]." (PMID 36545037, 2022).
hypophysitis (2 papers, 2016 to 2024). Inflammation of the pituitary gland. "However, the CRP values were trending higher at baseline in patients who developed hypophysitis than in the control group (p = 0.06)." (PMID 38611018, 2024). "Induction of hypophysitis, increased tumor antigen autoantibodies and CRP levels were observed." (PMID 27008709, 2016).
IgG4-related disease (2 papers, 2023 to 2025). "In IgG4-related disease (IgG4-RD), serum IL-6 levels significantly correlated with clinical inflammatory parameters such as serum CRP, hemoglobin, and albumin." (PMID 40692774, 2025).
Incisional hernia (2 papers, 2021 to 2023). An abdominal hernia that occurs at a site of weakness in the abdominal wall resulting from an incompletely-healed surgical wound. "Sixty-six patients were included in this study, one of the largest series in which the ability of CRP to predict complications after incisional hernia repair was evaluated and the first in which the focus was on the use of biological mesh." (PMID 33623063, 2021). "This suggests that CRP level is a predictor of complications in patients undergoing incisional hernia repair with a biological mesh." (PMID 33623063, 2021). "This study examined the ability of CRP measurements during the first 10 postoperative days to predict complications in patients who underwent incisional hernia repair using a biological mesh." (PMID 33623063, 2021). "Our results showed that not only the CRP level but also the WBC count predicted the development of postoperative complications after mesh-reinforced incisional hernia." (PMID 33623063, 2021). "For the occurrence of an incisional hernia, five risk factors were identified: the presence of COPD (p = 0.045); a preoperative CRP level above 5 mg/L (p = 0.005); the use of a midline incision (p = 0.041); and the postoperative occurrence of fascial dehiscence (p = 0.029) or SSI (p = 0.046)." (PMID 37109136, 2023). "A high postoperative CRP level (> 100 mg/L) up to POD10 may serve as a predictor of postoperative complications in patients undergoing incisional hernia using biological meshes." (PMID 33623063, 2021).
intestinal parasitic infection (2 papers, 2018 to 2024). "Our previous work on these pregnant women also revealed low protein status, multiple micronutrient deficiencies (folic acid, B12, vitamin A and D), inflammation measured through elevated C-reactive protein (CRP), and high prevalence of oral, skin, urogenital, and intestinal parasitic infections." (PMID 38892681, 2024).
iridocyclitis (2 papers, 2015 to 2023). "Higher SAA1 serum levels were demonstrated in JIA patients vs healthy CTR correlating with the number of active joints, iridocyclitis development, and high CRP and ESR expression, suggesting its potential as a disease activity marker." (PMID 37205098, 2023).
Kartagener Syndrome (2 papers, 2025 to 2026). An autosomal recessive disorder characterized by a triad of DEXTROCARDIA; INFERTILITY; and SINUSITIS. "In patient #5 with Kartagener’s syndrome and chronic bronchial P. aeruginosa infection, we observed a clinically significant increase in WBC count and CRP levels, despite no detectable change in physical symptoms of infection." (PMID 41516055, 2025).
lactose intolerance (2 papers, 2023 to 2025). "Here, we have used traits linked to dairy consumption—lactose intolerance and BMI—to dissect the role of dairy consumption on harmful inflammation as exemplified by RhA and serum concentration of CRP." (PMID 41502574, 2025). "Consistent with our analysis of RhA, we discovered a negative association between genetic liability to adult-onset lactose intolerance and serum CRP (IVW, p=0.03, beta=−0.01)." (PMID 41502574, 2025). "As an additional validation, we used the same set of instruments to determine whether adult-onset lactose intolerance is causally associated with the serum concentration of CRP." (PMID 41502574, 2025).
Left atrial enlargement (2 papers, 2022). Increase in size of the left atrium. "In addition to natriuretic peptide, C-reactive protein, galactose lectin-3 and left atrial enlargement can be used to predict the prognosis of HFpEF, but the predictive accuracy is not clear." (PMID 35224053, 2022).
leiomyosarcoma (2 papers, 2015 to 2022). An uncommon, aggressive malignant smooth muscle neoplasm, usually occurring in post-menopausal women. "Mean pre-treatment C-reactive protein (CRP) serum levels in patients with uterine leiomyosarcoma categorized by clinico-pathologic findings." (PMID 26248232, 2015). "In addition, disseminated tumors tend to cause higher spikes of CRP than localized tumors, which may not raise CRP at all (e.g., leiomyosarcoma, mammary gland tumors)." (PMID 36290272, 2022). "Due to the lack of valid prognostic markers for uterine leiomyosarcoma (ULMS) this study set out to investigate the value of pre-treatment CRP serum levels as prognostic parameter." (PMID 26248232, 2015).
lichen planus (2 papers, 2020 to 2025). A chronic, recurrent, pruritic inflammatory disorder of unknown etiology that affects the skin and mucus membranes. "However, further prospective studies may confirm the association between C-reactive protein-to-albumin ratio and lichen planus." (PMID 40172389, 2025). "Elevated C-reactive protein-to-albumin ratio levels may be considered a potential marker for lichen planus." (PMID 40172389, 2025). "Since lichen planus is a chronic inflammatory disease, our study aimed to investigate the relationship between C-reactive protein-to-albumin ratio and disease activity and whether it plays a role in determining disease prognosis, and compare them with those in subjects without lichen planus." (PMID 40172389, 2025).